CRP (C-reactive protein)
Diseases named in the same sentence as CRP in open-access papers (continued):
Sharing a sentence is not in itself a finding about the gene and the disease.
cardiovascular disease (continued). "In case of further pharmacological developments, cardiac glycosides may emerge as lead compounds for chemical modification in order to improve the potency, selectivity and pharmacokinetics of CRP synthesis inhibition in cardiovascular disease." (PMID 35407370, 2022). "This study finds that participants with high quality diet have favorable performance on several biomarkers, indicating a reduced risk for cardiovascular disease, such as “good” cholesterol (HDL), and measures of systemic inflammation, such as C-reactive protein." (PMID 35334855, 2022). "Cardiac glycosides may as well emerge as lead compounds for chemical modification in order to improve the potency, selectivity, and pharmacokinetics of CRP synthesis inhibition in cardiovascular disease." (PMID 35407370, 2022). "C-reactive protein is a common marker for both acute infection as well as inflammation, so it can be used as a marker of cardiovascular disease risk, although it is not a very specific prognostic indicator." (PMID 36381804, 2022). "The discordance of plasma Cystatin C levels with other renal function parameters such as plasma creatinine and urea could be influenced by multiple factors other than kidney function, such as cardiovascular disease and C-reactive protein levels." (PMID 35085251, 2022). "Therefore, we performed a systematic review and meta-analysis of randomized clinical trials (RCTs) evaluating the effect of statins on CRP and hs-CRP levels in patients with cardiovascular diseases (CVDs)." (PMID 35125965, 2022). "Patients with severe disease were characterised by older age (p < 0.001), increased BMI (p = 0.018), higher prevalence of cardiovascular disease (p = 0.001), lower lymphocytes (p = 0.005), and higher CRP (p < 0.001) and ferritin (p < 0.001) levels at the time of presentation." (PMID 35458517, 2022). "CRP has been reported to have an essential clinical significance in cardiovascular disease and AD." (PMID 36590920, 2022). "In a secondary analysis of the Canakinumab Anti-inflammatory Thrombosis Outcome Study (CANTOS) trial, it was found that patients who achieved the highest reduction in high sensitivity CRP as a result of canakinumab treatment had better cardiovascular disease outcomes." (PMID 36082127, 2022). "Moreover, the CALLISTO study found the TC/TG ratio was significantly correlated with high-sensitivity C-reactive protein levels that can predict cardiovascular disease." (PMID 36194621, 2022). "It should be mentioned that the participants in the study were relatively healthy and there was no consensus on the cut-offs for CRP in relation to cardiovascular disease risk, so the findings should be interpreted with care." (PMID 35458231, 2022). "Elevated levels of C-reactive protein (CRP) and urinary albumin-to-creatinine ratio were independently associated with ADL disability among older adults with cardiovascular disease, and subjects with higher levels of both markers had a more unfavorable metabolic profile than those with lower levels." (PMID 36003971, 2022). "CRP levels are also a powerful predictor of cardiovascular disease and metabolic syndrome." (PMID 36313504, 2022). "CRP is considered a cardiovascular disease marker that could be related to SLE clinical disease activity." (PMID 35407457, 2022). "Elevated CRP and IL6 levels are associated with various cardiovascular diseases." (PMID 34168680, 2021). "Whilst observational studies have shown that higher circulating CRP is associated with increased cardiovascular disease risk, MR studies suggest this is not a causal relationship." (PMID 33731105, 2021). "Univariate linear regression analyses demonstrated that serum FABP4, age, the history of cardiovascular disease, serum corrected calcium, corrected calcium >2.54 mmol/L, us-CRP, TG, body fat mass, body fat percentage, and lean body mass were positively associated with the AAC score (p < 0.1)." (PMID 34789046, 2021).
cardiovascular disease (continued). "Waist circumference has emerged as an important predictor of cardiovascular disease markers, such as elevated C-reactive protein, over the other MetS components for both sexes, though our findings suggest that this effect may be more robust for males." (PMID 34267647, 2021). "IL-6 and TNF-α stimulate the production of C-reactive protein by the liver, and together, they trigger the subclinical inflammation process, which in turn may result in the onset of cardiovascular diseases during adolescence." (PMID 34411143, 2021). "In addition, in misaligned individuals with similar sleep conditions to those in alignment, there was a significant increase in the levels of ultrasensitive C-reactive protein, a sign of systemic inflammation and a predictor of cardiovascular disease." (PMID 34209002, 2021). "CRP and cardiovascular diseases have been subject to an increasing body of research and debate." (PMID 32978716, 2021). "Therefore, elevated CRP levels have emerged as one of the most powerful independent predictors of cardiovascular disease." (PMID 33574979, 2021). "In support of this, suPAR predicted all-cause- and cardiovascular disease mortality independent of CRP and IL-6 in a South African population." (PMID 34925360, 2021). "The GPS is composed of hypersensitive C-reactive protein (H-CRP) and albumin, and H-CRP is widely recognized as one of the strongest risk indicators for predicting cardiovascular disease in addition to being considered an important marker of inflammatory factors." (PMID 34270463, 2021). "CRP evaluated with highly sensitive assays has been considered as the prototype serum inflammatory biomarker, with a proven strong predictive capacity in a wide array of cardiovascular disorders." (PMID 34362217, 2021). "Inhibitory monoclonal PCSK9 antibodies did not reduce highly sensitive CRP levels in patients with an increased risk for cardiovascular diseases." (PMID 33920491, 2021). "This pathogenesis of cardiovascular disease demonstrates how CRP, a biomarker reflecting the extent of inflammation, may predict the risk of cardiovascular events in all subjects, including apparently healthy adults." (PMID 33498799, 2021). "Besides IL-8, elevated levels of CRP and oxidized LDLs were found to positively correlate with cardiovascular diseases." (PMID 33467199, 2021). "Peripheral CRP and other proinflammatory markers were higher in winter in many studies in humans, and this is thought to contribute to seasonal prevalence of cardiovascular disease." (PMID 33817568, 2021). "Serum FABP4, age, and albumin remained significantly associated with the AAC score in PD patients after adjustment for the history of cardiovascular disease, systolic BP, diastolic BP, residual kidney Kt/V, serum corrected calcium, us-CRP, TG, HDL-C, skeletal muscle mass, and body fat mass." (PMID 34789046, 2021). "Therefore, some studies suggested that IL-6 is a biomarker with better sensitivity and characteristics than CRP for the diagnosis of cardiovascular disease." (PMID 34542791, 2021). "CRP has long been thought to be pathogenetically involved in human cardiovascular disease." (PMID 33778017, 2021). "A model assessed at day-5 of symptoms onset including male sex, age > 65 years, dyspnoea, cardiovascular disease, and at least three abnormal laboratory parameters among CRP (> 80 U/L), ALT (> 40 U/L), NLR (> 4.5), LDH (> 250 U/L), and CK (> 80 U/L) was proposed." (PMID 34454452, 2021). "This study aimed to investigate the linkage between serum markers of obesity and risk of cardiovascular diseases, with particular reference to the adipokines galectin-3, plasminogen activator inhibitor-1 (PAI-1), IL-1β, CRP, monocyte chemoattractant protein-1 (MCP-1), and insulin." (PMID 32290863, 2020). "CRP has been described as a biomarker of the inflammatory response with a significant prognostic value in a vast number of tumors as well as rheumatic and cardiovascular diseases." (PMID 32041109, 2020).
cardiovascular disease (continued). "Also, accepted markers of cardiovascular disease, such as c-reactive protein (CRP), correlate with 8-isoprostane (r = 0.097, p < 0.001)." (PMID 32498324, 2020). "C-reactive protein (CRP) is a stable inflammation marker and predictor of cardiovascular diseases." (PMID 32294936, 2020). "It has been apparent that CRP is not a reliable predictive marker of cardiovascular disease or underlying inflammation in SLE patients as it is in other conditions." (PMID 32182251, 2020). "Consequently, “classic” cardiac biomarkers like BNP or troponin, but also inflammatory biomarkers like C-reactive protein (CRP) or high-sensitive (hsCRP), have improved general diagnostic efficiency in various cardiovascular diseases like CAD or HF." (PMID 32093244, 2020). "While CRP is mostly used as sensitive acute-phase parameter indicating inflammation, baseline serum levels in adults are influenced by age, smoking, lipids, oral contraceptives, and cardiovascular diseases." (PMID 32154197, 2020). "The lack of association between CRP and anti-PC antibodies does not support an anti-inflammatory mechanism behind the latter’s inverse association with cardiovascular disease." (PMID 33334321, 2020). "These authors suggested that a satisfactory inflammation profile, as verified by low CRP levels, could play a role in the protective profile of the MHO individual and that this may be related metabolically to a lower risk of cardiovascular disease." (PMID 34290747, 2020). "In sensitivity analyses, the hazards associated with ALC, RDW, and CRP level did not diminish with exclusion of individuals with preexisting cardiovascular disease or malignant disease." (PMID 31790569, 2019). "Air pollution was linked to changes in markers of coagulation (fibrinogen), inflammation (C-reactive protein), and endothelial function (ICAM-1 and VCAM-1), that may influence risk of cardiovascular disease." (PMID 31703266, 2019). "Several predictors such as high laboratory result for C-reactive protein (CRP), longer duration of disease, older age, history of known cardiovascular disease, and history of tobacco smoking may predict the incidence of peripheral vascular events in SLE." (PMID 31018871, 2019). "Furthermore, subjects with high levels of CRP showed a higher prevalence of cardiovascular disease (CVD) at baseline." (PMID 30872696, 2019). "Chronic elevation of CRP levels is therefore strongly indicative of a chronic pro-inflammatory state and persistently elevated CRP is a strong predictor of cardiovascular disease development, independent of traditional risk factors." (PMID 30692559, 2019). "Apart these aspects, social integration was related to chronic low-grade inflammation with lower levels of inflammatory cytokines include interleukin (IL)-1, tumor necrosis factor (TNF), and C-reactive protein, which appears critical in the progression of cardiovascular disorders." (PMID 31035622, 2019). "Here, we assessed whether low serum PON1 activity associates with incident cardiovascular disease (CVD) in subjects with high levels of high-density cholesterol (HDL-C) and C-reactive protein (CRP), a marker of low-grade systemic inflammation." (PMID 31480611, 2019). "Furthermore, red meat intake has been associated with increased levels of inflammatory and oxidative stress markers such as C-reactive protein (CRP) and gamma-glutamyl transferase (GGT) that have been associated with cardiovascular diseases." (PMID 30875776, 2019). "For decades, CRP has been regarded only as a hallmark of inflammation; however, it has since been recognised as a significant predictor of future episodes of cardiovascular disease, independent of other risk factors." (PMID 31151201, 2019). "The preferred inflammatory biomarker in cardiovascular disease is CRP." (PMID 30619885, 2018).
cardiovascular disease (continued). "Furthermore, previous studies suggested that nuts consumption is related to improvements in inflammatory markers including C-reactive protein (CRP), an independent risk factor of cardiovascular disease (CVD)." (PMID 30131846, 2018). "Several studies support the concept that hs-CRP is a predictor of cardiovascular disease and T2DM." (PMID 29721105, 2018). "Besides its role in the humoral innate immune response, CRP contributes to cardiovascular disease progression by recognizing and binding multiple intrinsic ligands." (PMID 29552019, 2018). "Vitamin C supplementation may be another potential treatment modality as it is decreased in patients with ICH and supplementation has reduced CRP levels in patients with cardiovascular disease." (PMID 30613458, 2018). "Adjustments in a full model composed of age, BMI, smoking, prevalent cardiovascular disease and levels of calcium, 25-hydroxyvitamin D, eGFR, CRP, Mg, glucose and total cholesterol to HDL cholesterol ratio levels did not substantially modify results (men: 1.49 (1.27–1.74); women: 0.92 (0.79–1.07))." (PMID 29766437, 2018). "Additionally, A very large number of studies have indicated that hypersensitive C-reactive protein (Hs-CRP) was a useful inflammatory marker for judging the prognostic outcomes in a variety of cardiovascular diseases." (PMID 30470229, 2018). "In subjects without clinical cardiovascular disease, CRP has been associated with differences in RV morphology as assessed by MRI." (PMID 30114262, 2018). "Cardiovascular disease (CVD) and VTE are closely linked and share common antecedent risk factors, and there is an evolving debate that inflammation or CRP might also be linked to the development of VTE; however, the emerging evidence is controversial." (PMID 28718029, 2017). "Given the correlations between the HRV marker Stress Index and CAN score with CRP, the ANS-1 system may also prove to be an excellent screening tool for early cardiovascular disease and/or an assessment of cardiovascular risk." (PMID 28616394, 2017). "Moreover, the inflammatory cytokine CRP is considered to be an indicator of systemic low-grade inflammation and an active mediator of cardiovascular disease." (PMID 28837559, 2017). "CRP was associated with fatal and nonfatal cardiovascular disease events as well as nonfatal PAD events in 18,450 apparently healthy participants in the European Prospective Investigation into Cancer and Nutrition-Norfolk cohort." (PMID 28298189, 2017). "Detection of the slight elevations of CRP associated with an increased risk of cardiovascular disease, ≥ 2 mg/L, requires a “high-sensitivity” CRP assay, not the routine assay used to assess inflammation in other diseases." (PMID 29435395, 2017). "So NLR is not an inflammatory marker only but also a direct cause of cardiovascular disease in diabetic patients like CRP." (PMID 29492060, 2017). "Inflammatory markers such as C-reactive protein (CRP) and IL-6 can be used to predict cardiovascular diseases and severity of HF while fibrotic markers such as Gal-3 and syndecan-1 are currently used for risk stratification in HF, predicting mortality or readmission." (PMID 28707261, 2017). "High-sensitivity C-reactive protein (hs-CRP) is detected using advanced techniques of high-sensitivity assays, and its elevated level from the reference range predicts an increased risk of cardiovascular disease." (PMID 28946611, 2017). "Randomized controlled trials of aspirin conducted among patients with cardiovascular disease found statistically significant reductions in circulating concentrations of high-sensitivity C-reactive protein (CRP), tumor necrosis factor-alpha (TNF-α), interleukin-6 (IL-6), and thromboxane B2 (TXB2)." (PMID 28542447, 2017). "High levels of C-reactive protein have been related to cardiovascular disease." (PMID 26967543, 2016).
cardiovascular disease (continued). "Studies on the added value of CRP in risk prediction of cardiovascular disease show that hs-CRP levels can confirm the presence of plaques but do not provide insight on the degree of stenosis or the inflammation in the plaque." (PMID 27051078, 2016). "The association of AHRR methylation with CRP and incident CHD may highlight a connection between CRP and cardiovascular disease that is shared between cigarette smoking and independent mechanisms." (PMID 27955697, 2016). "The CRP level has been shown to independently predict future cardiovascular events and seems to have the most established position in prevention and management of cardiovascular diseases." (PMID 27044376, 2016). "Recent reports showed that the level of CRP could predict patient outcomes in cardiovascular disease." (PMID 27699084, 2016). "Additionally, both proteins are associated with increased risk for cardiovascular diseases (CVD), where an increase of 10% of CRP levels leads to a 5.5% increase in CVD risk and a twofold increase of SAA1 to a 17% increase." (PMID 28007936, 2016). "Furthermore, the participants lost to follow-up had higher CRP and lower HDL-levels, two possible risk factors for cardiovascular disease, compared to the ones who remained in the study." (PMID 27146485, 2016). "Damaged hepatocytes release increased amounts of C-reactive protein (CRP) and coagulation factors, which could contribute to increased risk of cardiovascular disease and atherothrombotic vascular disease." (PMID 27128911, 2016). "Furthermore, in patients with both COPD and cardiovascular disease, increasing C-reactive protein levels are present, which confirms the presence of a systemic inflammation." (PMID 27275236, 2015). "Framingham risk scores (FRS), Reynolds risk score, highly sensitive C-reactive protein (hs-CRP), carotid intima media thickness (CIMT) and coronary artery calcium (CAC) are among the various measures that can be used for screening of cardiovascular disease among asymptomatic population." (PMID 25807266, 2015). "CRP is a nonspecific marker for inflammation, but has been used to risk stratify subjects for cardiovascular disease." (PMID 25827220, 2015). "Epidemiological data underline this notion and show increased C5a levels in patients with increased cardiovascular disease risk, independent of non-specific inflammatory markers such as C-reactive protein (CRP) or fibrinogen." (PMID 25784879, 2015). "However, the potential interaction between hs-CRP and concurrent disease, such as cardiovascular disease and chronic HBV infection, should be further explored." (PMID 25874450, 2015). "Importantly, these same variants are documented determinants of important cardiovascular disease risk factors (total, LDL, and HDL cholesterol, triglycerides, CRP and proinflammatory eicosanoids)." (PMID 24842322, 2014). "It was demonstrated several years ago that both constitutive and IL-6-dependent acute-phase expression of the CRP transgene in mice requires testosterone, restricting meaningful experimental analyses of the role of CRP in cardiovascular disease to male CRP transgenic mice." (PMID 24872599, 2014). "CRP specific ASOs might pave the way towards a placebo-controlled trial that could clarify the role of CRP in cardiovascular disease." (PMID 24803739, 2014). "Moreover, reduced exercise tolerance and higher plasmatic C-reactive protein levels were found in the obese patients, who also presented a greater prevalence of cardiovascular disease (adjusted odds ratio 4.796, 95%CI 1.806–12.736, p = 0.002)." (PMID 25153331, 2014). "The most extensively studied biomarkers of inflammation in cardiovascular disease are CRP and IL-6." (PMID 24782595, 2014). "RA has a higher level of CRP and more pronounced traditional cardiovascular risk factors than IBD, which may contribute to the difference in their associations with cardiovascular disease and mortality." (PMID 25337037, 2014).